HLA-B (major histocompatibility complex, class I, B)
Diseases named in the same sentence as HLA-B in open-access papers (continued):
Sharing a sentence is not in itself a finding about the gene and the disease.
lung carcinoma (10 papers, 2003 to 2025). "This variant is in high LD (r2 = 0.76) with HLAB*0801, therefore within AH8.1, and was reported as associated with SCC in the largest lung cancer GWAs published to date." (PMID 30254314, 2018). "Of the remaining genes, only HLA-B appeared as being significant in other lung carcinoma papers investigated." (PMID 19259419, 2008). "In addition, from the set of 49 lung cancer genes, we found that HLA-C had the fourth, HLA-B had the seventh and HLA-A had the eighth highest frequency of alternative splicing." (PMID 39358601, 2024). "Finally, we observed increased HLA-B levels in correlation with tumor infiltration across the TCGA lung cancer cohorts." (PMID 30833945, 2019). "Notably, HLA-B and HLA-C are linked to smoking-associated ailments, including COPD and lung cancer." (PMID 38672772, 2024). "As an example, the Jcomp score across the 11 lung cancer tissues was positively correlated with the expression of genes coding MHC-class I protein (B2M, HLA-A, HLA-B, and HLA-C), which are among the biomarkers for immunotherapy response." (PMID 40170080, 2025). "For lung cancer, we found three cancer driver genes (HLA-A, CASP8 and LEMD2) and two CGC genes (HLA-A and CASP8) among the unreported genes, and one cancer driver gene (HLA-B) and one CGC gene (FGFR1OP) among the previously reported genes." (PMID 36402776, 2022).
hypersensitivity reaction (9 papers, 2010 to 2023). "A case-control study was performed by genotyping the HLA-B alleles of Thai carbamazepine-induced hypersensitivity reaction patients (17 MPE, 16 SJS/TEN, and 5 DRESS) and 271 carbamazepine-tolerant controls." (PMID 29546073, 2018). "HIV treatment guidelines now endorse the use of prospective HLA-B*5701 screening in patients before initiating an ABC-containing regimen to reduce the risk of developing a abacavir hypersensitivity reaction." (PMID 23741991, 2013). "In addition, the presence of HLA-B*5701 was associated with clinically diagnosed hypersensitivity reaction in Hispanic and Thai patients infected with HIV." (PMID 26300948, 2015). "Therefore, if laboratories provided HLA-B typing with high-resolution results, instead of testing only for specific alleles, alternative drugs could be considered for this patient to reduce the risk of a severe hypersensitivity reaction." (PMID 37424729, 2023). "The uptake of HLA-B*57:01 screening and incidence of hypersensitivity reaction were assessed in a prospective clinical cohort in the United States to evaluate the effectiveness of this intervention." (PMID 30651100, 2019). "For example, associations have been reported to exist between HLA-B*57:01 and abacavir-induced hypersensitivity reactions, HLA-B*15:02 and carbamazepine-induced SJS/TEN, and HLA-B*58:01 and allopurinol-induced SCARs (SJS/TEN and DIHS/DRESS)." (PMID 33670052, 2021).
inflammatory bowel disease (9 papers, 2020 to 2025). A spectrum of small and large bowel inflammatory diseases of unknown etiology. "HLA-B*27 is likely to increase the likelihood of having axSpA features in those with inflammatory bowel disease." (PMID 33763060, 2021). "Recently, we have reported the frequent co-occurrence of Takayasu arteritis and ulcerative colitis, one of the inflammatory bowel diseases (IBD), driven by HLA-B*52:01." (PMID 35534869, 2022).
schizophrenia (9 papers, 2008 to 2022). A major psychotic disorder characterized by abnormalities in the perception or expression of reality. "Nevertheless, our sex-dependent finding is particularly interesting in light of recent work demonstrating that HLA-B matching as a schizophrenia risk factor is limited to females." (PMID 18692992, 2008). "A previous study found that mutations in human leukocyte antigen B (HLA-B) in the prefrontal lobe may affect dopamine signaling in the central nervous system and indirectly influence the development of schizophrenia." (PMID 35855328, 2022). "Interestingly, HLA-B has been implicated in schizophrenia; however, the increase in risk was the result of matching HLA-B genotypes in the mother and the child." (PMID 24433325, 2014). "HLA class I genes such as HLA-A, HLA-B and HLA-C are located in the MHC region and are included in the schizophrenia specific module, S_R_only_M1, from our replication study." (PMID 27898074, 2016). "Regarding the HLA system, studies to date have reported negative correlations between HLA-C*07 and schizophrenia and positive correlations between HLA-B*58:01, C*07:01, DQA1*01:01, DQB1*05:01, and DPB1*17:01 and posttraumatic stress disorders." (PMID 36231907, 2022).
epilepsy (8 papers, 2015 to 2025). A brain disorder characterized by episodes of abnormally increased neuronal discharge resulting in transient episodes of sensory or motor neurological dysfunction, or psychic dysfunction. "Frequency of the HLA-B*1,502 allele contributing to carbamazepine-induced hypersensitivity reactions in a cohort of Malaysian epilepsy patients." (PMID 40873549, 2025). "HLA-B*13:02 allele has been nominally associated with lamotrigine (an antiepileptic drug used to treat epilepsy and bipolar disorder)-induced SCAR in the Korean population." (PMID 39464636, 2024). "Association of HLA-B*15:02 with CBZ-induced SJS/TEN was confirmed in Malay and Chinese epilepsy patients." (PMID 40873549, 2025). "In particular, genes such as ANXA1, CNTN6, HLA-B, PCDH19, and PCDH10, have been linked to ASD, epilepsy, ID, and other neuropsychiatric disorders, were significantly upregulated or downregulated and warrant further investigation." (PMID 31921404, 2020). "As a result, the Thai government is now providing HLA-B*15:02 testing as a standard of care, while the same findings were reported for the Singaporean population, when cost-effectiveness of HLA-B*1502 genotyping in adult patients with newly diagnosed epilepsy was assessed." (PMID 26081768, 2015). "The study in Thailand showed that HLA-B*15:02 screening would be cost-effective in CBZ-treated patients with neuropathic pain but not for epilepsy because the cost of alternative drugs for epilepsy was approximately two times higher than the cost for neuropathic pain." (PMID 34600523, 2021).
glioma (8 papers, 2016 to 2025). A benign or malignant brain and spinal cord tumor that arises from glial cells (astrocytes, oligodendrocytes, ependymal cells). "Another two similar neoepitopes from H3 K27M mutations, MSAPATGGV and MSAPSTGGV, were predicted to bind HLA-B*15:17, HLA-A*68:02, HLA-A*02:05, HLA-C*12:03, or HLA-C*03:04 alleles in nine different high-grade glioma patients." (PMID 28854978, 2017). "In a previous study based on HLA antigen frequencies in patients with glioma, patients positive for HLA-A*25 had a 3.0-fold increased risk of glioma (P = 0.04) and patients positive for HLA-B*27, a 2.7-fold risk (P = 0.03), compared with the control population." (PMID 36333286, 2022). "HLA-I supertypes were largely represented among the PDX models: all 5 HLA-A supertypes in sarcoma, neuroblastoma, high-grade glioma PDXs, and 5–7 HLA-B supertypes in sarcoma and neuroblastoma." (PMID 37723198, 2023). "The results of the DEG co-expression network showed that the HLA family (HLA-A, HLA-B, HLA-C, HLA-E, HLA-DRA, HLA-DRB1, and CD74 [HLADG]) plays a vital role in the network, suggesting that tumor immunity is involved in glioma formation." (PMID 34660294, 2021).
pancreatic cancer (8 papers, 2016 to 2025). "Nevertheless, WDR5 expression exhibits a positive correlation with HLA level in human cancer cells, and H3K4me3 enrichment is found at the promoter regions of the HLA-A, HLA-B, and HLA-C genes in pancreatic cancer cells based on an Encode database analysis." (PMID 39201460, 2024). "In conclusion, these results suggest that the combination of HLA-B*15:01 and DRB1*15:01 is associated with ILD in Japanese patients with advanced pancreatic cancer receiving gemcitabine plus erlotinib." (PMID 27100735, 2016). "However, WDR5 expression is positively correlated with the HLA level in human cancer cells, and H3K4me3 enrichment is observed at the promoter region of the HLA-A, HLA-B, and HLA-C genes in pancreatic cancer cells." (PMID 39201460, 2024). "Using flow cytometry, we monitored MHC class I expression with the BB7.2 antibody that recognizes peptide-bound HLA-A2 (an MHC class I molecule that is expressed by S2-013 pancreatic cancer cells), and with an antibody that recognizes HLA-B and HLA-C (B1.23.2)." (PMID 36126055, 2022). "Our results demonstrate that the combination of HLA-B*15:01 and DRB1*15:01 is over-represented significantly in Japanese patients with advanced pancreatic cancer who developed ILD after the treatment with gemcitabine plus erlotinib." (PMID 27100735, 2016). "Furthermore, on the pairwise colocalization effect of CD29 with HLA-ABC, certain isotypes of HLA-B are able to decrease ITGB1 expression and affect pancreatic cancer cell migration with contrasting effects." (PMID 38983848, 2024). "To determine if the expression of MHC class I heavy chain proteins in pancreatic cancer cells is increased by M344 treatment, we performed immunoblot analysis on lysates of M344-treated S2-013 pancreatic cancer cells with an antibody recognizing the human MHC class I heavy chains HLA-B and HLA-C." (PMID 36126055, 2022).
reactive arthritis (8 papers, 2017 to 2025). Reactive arthritis (ReA) is an autoimmune disorder belonging to the group of seronegative spondyloarthropathies and is characterized by the classic triad of arthritis, urethritis and conjunctivitis. "In a study from the UK, where the frequency of HLA-B*27 is roughly 8%, it was found to be associated with 60–90% of patients with reactive arthritis." (PMID 33910121, 2021). "Given the high incidence of infection, particularly with causative agents of reactive arthritis such as Shigella and C. jejuni/coli, paired with the frequency of HLA-B*27 it is plausible these infants may experience increased risk for reactive arthritis later in life." (PMID 33910121, 2021). "In the subgroup of patients with reactive arthritis, HLA-B*37 and HLA-B*41 appeared disproportionately represented." (PMID 40806743, 2025). "However, HLA-B*37, although overall rare, was detected in 13.33% of patients with dactylitis and in 20% of those with reactive arthritis, underscoring the possibility of subtype-specific associations not captured in aggregate analyses." (PMID 40806743, 2025). "Imputation of classical human leukocyte antigen (HLA) types from genomic and transcriptomic data identified HLA-B*27:05, previously associated with nontyphoidal Salmonella-induced reactive arthritis, as the HLA type most strongly associated with enteric fever susceptibility (P = 0.011)." (PMID 35254093, 2022). "C1R cells were used as they have no surface HLA-A/B expression, express large amounts of HLA-B*27, and have previously been used in a number of experiments to explore the contribution of HLA-B*27 to S. Typhimurium- and S. Enteritidis-induced reactive arthritis." (PMID 35254093, 2022).
skin reaction (8 papers, 2017 to 2026). "For instance, the human leukocyte antigen (HLA-B*15:02) allele was found to be highly associated with carbamazepine-induced severe skin reactions in broad Asian populations." (PMID 41018203, 2025). "Carrying out HLA-B*15:02 allele genotyping helps guide treatment selection by identifying individuals with an increased risk of severe skin reactions to carbamazepine." (PMID 41018203, 2025). "Regardless, as oxcarbazepine carries the risk of severe skin reactions, testing for the high-risk HLA-B*1502 allele in patients with relevant ancestry (i.e., genetically at-risk populations) would be beneficial." (PMID 34108928, 2021). "However, little is known about allopurinol-induced skin reactions in Kinh Vietnamese population, particularly the clinical risk factors and the association with HLA-B*58:01." (PMID 32746911, 2020). "An association between HLA-B*1502 allele and severe skin reactions have been reported." (PMID 28698724, 2017). "A research team from Taiwan first found the risk of allopurinol-induced severe skin reactions is 580.3 times higher in HLA-B*58:01 carriers than noncarriers in Han Chinese patients." (PMID 33981213, 2021).
squamous cell carcinoma (8 papers, 2014 to 2023). A carcinoma arising from squamous epithelial cells. "A reduced risk of squamous cell carcinoma was seen with both HLA Class I (HLA-B*15 (OR = 0.55, P = 4.78 × 10−6)) and HLA Class II alleles (HLA-DQA1*0103 (OR = 0.69, P = 0.006), HLA-DRB1*13 (OR = 0.71, P = 5.27 × 10−4), HLA-DQB1*0603 (OR = 0.69, P = 0.007))." (PMID 28806749, 2017). "They found novel somatic mutations in the MAPK1 gene (8%), HLA-B gene (9%), EP300 (16%), FBXW7 (15%), NFE2L2 (4%), and ERBB2 (6%) of 79 squamous carcinomas, and ELF3 (13%) and CBFB (8%) mutations in 24 adenocarcinomas." (PMID 26701206, 2016). "In addition to the strong reduced risk of cervical neoplasia associated with HLA-B*15, the haplotype HLA-DRB1*1301/HLA-DQB1*0603 (and in some analyses HLA-DQA1*0103) was associated with reduced risk of squamous cell cancer, adenocarcinoma, and HPV16- and HPV18-related cervical neoplasia." (PMID 28806749, 2017).
co-infection (7 papers, 2014 to 2021). "Our patient presented all the risk factors: EBV reactivation with CMV co-infection; intensified immunosuppressive therapy during both rejection episodes; HLA mismatches, particularly for HLA-B." (PMID 24942882, 2014). "If this is the case, it might be predicted that individuals with HLA-B*44:03 might be at particular risk, not only of reduced ability to counter infections in later life, but also to combat coinfections such as HIV which also appear to induce large T cell expansions." (PMID 30487790, 2018). "We therefore investigated the phenotypic diversity of CD56dim NK cell subset to delineate the fingerprint of HCMV co-infection in the three study groups in relation to the presence of -21 HLA-B dimorphism." (PMID 32132995, 2020). "This re-analysis confirmed HLA-B*57 as a risk factor in HIV infection (log-rank p = 0.038) and HIV/HCV co-infection (log-rank and Cox regression p = 0.001 each; OR 3.663, 95% confidence interval 1.688–8.005)." (PMID 26241854, 2015). "The increased mortality risk associated with HLA-B*57 was identified by Kaplan-Meier analysis and confirmed by logistic regression analysis both in the patients with HIV/HCV co-infection and the entire population of HIV-infected patients." (PMID 26241854, 2015). "They predominantly expressed African specific HLA-B and -C alleles that contribute a distinct supply of NKG2A and KIR ligands, and these genetic differences were compounded by the marked effect of HIV-1/HCMV co-infection on NK cell differentiation." (PMID 32132995, 2020). "Increased mortality of HLA-B*57-positive patients was confirmed by Kaplan Meier analysis in both HIV infection (p = 0.032) and HIV/HCV co-infection (p = 0.004)." (PMID 26241854, 2015). "The frequency of patients with HLA-B*57 was increased in patients with HIV infection (12.9%) and reduced in patients with hepatitis C (4.2%) as compared to patients with HIV/HCV co-infection (8%) and the healthy background population (9.2%)." (PMID 26241854, 2015). "The remaining 468 patients (HLA-A n = 414, HLA-B n = 468) constitute the available study population, comprising 186 patients with HIV infection, 120 patients with chronic hepatitis C, and 162 patients with HIV/HCV co-infection." (PMID 26241854, 2015). "Here, we report the novel and unexpected observation that in such a population HLA-B*57 may adversely affect long-term survival, particularly in HIV/HCV co-infection." (PMID 26241854, 2015).
colorectal cancer (7 papers, 2011 to 2026). A primary or metastatic malignant neoplasm that affects the colon or rectum. "Based on the study of the immunologic subclassification of colorectal cancers with high microsatellite instability, the decrease in TILs is partly attributed to the downregulation of HLA-A, HLA-B, and HLA-C." (PMID 37190307, 2023). "T cells and HLA-B/C antigens play an important role in controlling colorectal cancer growth, and the upregulation of HLA-B/C may trigger or enhance T-cell immunity." (PMID 38068961, 2023). "The present immunohistochemical study of colorectal carcinoma lesions with the MEM-E/02 antibody reveals that high expression of HLA-E significantly correlates with high expression of HLA-A, but not HLA-B or HLA-C." (PMID 22032294, 2011).
hypersensitivity (7 papers, 2015 to 2025). An inflammatory response to an exogenous environmental antigen or an endogenous antigen initiated by the adaptive immune system. "A classic example in pharmacogenomics is the antiretroviral drug abacavir, where the presence of the HLA-B*57:01 allele can predispose patients to a hypersensitivity reaction." (PMID 38256367, 2024). "One of the most successful applications of pharmacogenetics research is the genetic screening for HLA-B*57:01, strongly associated with an increased risk to develop hypersensitivity reaction in HIV-positive patients following abacavir administration." (PMID 25201286, 2015). "According to previous studies and the CPIC guideline, the genotyping of the HLA-B*57:01 variant in the HLA-B gene is useful for identifying patients most likely to present hypersensitivity reactions, which consist of dyspnea, rash, fatigue, pyrexia, gastrointestinal symptoms, and cough." (PMID 39858601, 2025). "HLA-B*5701 testing for all flucloxacillin starters is estimated to prevent 22 hypersensitivity reactions and 2 deaths per year, but almost 300,000 people would need to be genotyped for HLA-B*5701 each year." (PMID 35056062, 2021). "Han people with the GG genotype of rs9263726 represent non-HLA-B*58:01 carriers and could take allopurinol without high risk of a hypersensitivity reaction." (PMID 30080910, 2018).
neutropenia (7 papers, 2017 to 2025). A decrease in the number of neutrophils found in the blood. "Clozapine pharmacokinetics is influenced by CYP3A4 and CYP3A5 activity, as well as polymorphisms in HLA-B that can cause clozapine-induced neutropenia." (PMID 35722694, 2022). "Based on this finding, a re-challenging with clozapine following neutropenia in a patient with a low risk of CIAG (HLA-B*52:01/52:01) was successfully conducted." (PMID 30319405, 2018). "We now know that the genetic etiology of clozapine-associated neutropenia is complex and is likely to involve variants from several genes including HLA-DQB1, HLA-B and SLCO1B3/SLCO1B7." (PMID 30767710, 2019). "A combined GWAS meta-analysis in a sample of patients of Chinese ancestry identified a nominal association between rs11753309 near HLA-B and clozapine-induced neutropenia; however, this GWAS was not included in the meta-analysis as the results are not specific to CIA." (PMID 35710824, 2022).